GSPT1 (G1 to S phase transition 1)
Diseases named in the same sentence as GSPT1 in open-access papers (continued):
Sharing a sentence is not in itself a finding about the gene and the disease.
cancer (continued). "To further explore the therapeutic potential of GSPT1 MGDs in hematological cancers, we evaluated the anti-cancer activities of CYRS381 in AML models." (PMID 40551250, 2025). "In this study, we identified that the expression level of CRBN, a subunit of the E3 ligase complex, is a critical determinant of cancer cell responsiveness to GSPT1-targeting MGDs." (PMID 40551250, 2025). "Although CRBN is often regarded as ubiquitously expressed, our research reveals significant expression differences across various cancer cell lineages that are critical for determining cellular responsiveness to GSPT1 MGDs." (PMID 40551250, 2025). "In conclusion, this study highlights the therapeutic potential of GSPT1 MGDs in CRBN-high cancers, such as NECs and AML." (PMID 40551250, 2025). "Few studies have examined the relationship between GSPT1 expression and the prognosis of patients with cancer." (PMID 39117611, 2024). "These developments suggest a growing interest in exploiting GSPT1 as a therapeutic target across different cancer types, with the potential to significantly enhance treatment outcomes." (PMID 39500878, 2024). "This revealed E14 as a potent MG degrader targeting IKZF1/3, GSPT1 and 2 with profound effects on a panel of cancer cells." (PMID 38114468, 2023). "The recent discovery of thalidomide analogs that degrade G1 to S phase transition 1 (GSPT1) via the CRL4CRBN ubiquitin ligase highlighted GSPT1 as a novel potential therapeutic target in the treatment of cancer." (PMID 35763353, 2022). "CRBN-mediated GSPT1 degradation by the next-generation CRBN modulator CC-885 has been shown to have a strong antiproliferative effect in most cancer cell lines with adequate CRBN expression and activity." (PMID 34215850, 2021). "We found that NL4-3, but not 81A, up-regulated many genes in human MDM, including TNF2, Fas (TNFRSF6)-associated via death domain, caspase-7, Cytocrome C, KGF and GSPT1/eRF3 but down-regulates survival and cancer genes." (PMID 31234437, 2019). "GSPT1 is a GTPase involved in protein translation whose disruption may offer therapeutic potential in translation-dependent cancers." (PMID 41652432, 2026). "In addition, in most cancer types, except for CHIP and DCAF15, other ligases are highly associated with GSPT1." (PMID 41194439, 2025). "GSPT1, especially GSPT1‐005, is upregulated in various cancers, indicating that the upregulated GSPT1 may drive tumor growth through the translation termination process." (PMID 41194439, 2025). "Above all, we proposed that the mechanisms of GSPT1 promoting cancer progression may be abnormal expressions of GSPT1 isoforms." (PMID 41194439, 2025). "Consistent with the observation that GSPT1 degradation kinetics differ depending on cell type, analysis of TCGA pan-cancer datasets revealed that CRBN and DDB1 mRNA levels were positively correlated with NE gene signature scores and inversely correlated with non-NE gene signature scores." (PMID 40551250, 2025). "G1 to S phase transition protein (GSPT1), a small GTPase involved in translation termination, which promotes the progression of cancer cells, has emerged as an attractive potential therapeutic target for cancer treatment with the rapid breakthrough of molecular glue degraders (MGDs)." (PMID 41194439, 2025). "Although gene essentiality assessment for GSPT1 through CRISPR loss‐of‐function screens in a wide range of cancer cell lines derived from Cancer DepMap Portal verified that almost all cancer cells are dependent on GSPT1 effects, the precise mechanism of GSPT1 modulation remains to be elucidated." (PMID 41194439, 2025). "Moreover, we also investigated GSPT1 expression patterns, including isoform‐specific expression in pan‐cancer." (PMID 41194439, 2025).
cancer (continued). "According to a heatmap of single‐cell GSPT1 mRNA expression in major‐lineage pan‐cancer retrieved from TISCH based on scRNA‐seq, GSPT1 is highly expressed in immune cells, particularly in Treg cells and CD8 T cells, which infiltrate the cells of PRAD, THCA, NSCLC, LIHC, HNSC, ESCA, and CRC." (PMID 41194439, 2025). "Thus, pan‐cancer immune infiltration analysis was performed to further explore the correlation between the expression of GSPT1 and tumor microenvironment remodeling." (PMID 41194439, 2025). "Therefore, a comprehensive and systematic understanding of GSPT1 is urgently needed to provide a pharmacological perspective for targeted therapies in abnormal GSPT1‐driven cancer." (PMID 41194439, 2025). "Myc‐addicted tumours, which may represent up to 70% of all human cancers, are indeed highly dependent on protein synthesis, for which GSPT1 is a rate‐limiting factor of the translation termination step." (PMID 40266852, 2025). "Research on how these cancer‐related pathways interact with GSPT1 in cancer biology may be one future topic." (PMID 41194439, 2025). "We further explored the isoform‐specific expression of GSPT1 in TCGA pan‐cancer derived from RNA‐seq data, to explore whether the correlation between GSPT1 expression and cancer progression is related to different isoforms." (PMID 41194439, 2025). "Therefore, we systematically summarized the signaling pathways of GSPT1 in cancer cells and discussed the molecular and biological role of GSPT1 in cancer in comparison to its physiological functions to promote understanding of the significance of GSPT1 in health and disease." (PMID 41194439, 2025). "G1 to S phase transition protein (GSPT1), a small GTPase previously “undruggable target” involved in translation termination, has emerged as a potential therapeutic target for the treatment of cancer with the rapid breakthrough of targeted protein degradation (TPD) technology." (PMID 41194439, 2025). "Considering the immunosuppressive effect of GSPT1, the combination of GSPT1 degraders and immunotherapy, including PD‐1 inhibitors, may inhibit tumor growth, activate immune attacks, disrupt immune escape, and enhance anti‐cancer efficacy." (PMID 41194439, 2025). "Therefore, GSPT1 could be a reasonable downstream gene of hsa_circ_0001944 to exert its cancer‐promoting effect." (PMID 36597856, 2023). "As increased translation is a common feature of cancer, this provides a potential mechanism whereby normal stem cells would be relatively protected from CC-885 and potentially other drugs targeting GSPT1, providing additional rationale for GSPT1 as a clinical target." (PMID 35763353, 2022). "Unlike the universal lethality observed with GSPT1 gene knockout, only cancer cells with a high degree of NE differentiation, characterized by elevated CRBN expression, displayed selective responsiveness to GSPT1 MGDs." (PMID 40551250, 2025). "By identifying the synthetic lethal partner of GSPT1, researchers hope to identify more sensitive indications for targeting GSPT1, including MYC, IKZF1/3, BTK, AR/ARv7, and mTOR‐driven cancers." (PMID 41194439, 2025). "To evaluate the effects of the GSPT1 MGD on cancer cells, we utilized CYRS381 (previously known as SJ6986), an orally bioavailable and well-characterized GSPT1 MGD." (PMID 40551250, 2025). "Through the pan‐cancer datasets (The Cancer Genome Atlas, TCGA+TARGET+GTEx) downloaded from UCSC, we compared the mRNA levels of GSPT1 between tumor tissues and normal tissues across 34 tumors." (PMID 41194439, 2025). "Classic examples include thalidomide, which was repurposed for its anti-cancer properties, CC885, which targets the translation termination factor GSPT1, and E7070, an anti-cancer sulfonamide." (PMID 40854914, 2025). "In cancers that are non‐responsive to MDM2 degradation alone, WB156 acts as a GSPT1 degrader to induce anti‐proliferative effects." (PMID 41194439, 2025).
cancer (continued). "GBD-9 efficiently degraded BTK and GSPT1 proteins with high efficiency (BTK (90%) and GSPT1 (80%) at 50 nM concentration) and inhibited cancer cell growth by recruiting CRBN in a range of DLBCL and AML cell lines." (PMID 40793752, 2025). "Degradation of GSPT1 and the resulting impaired translation termination and activation of the ISR are a new approach to cancer treatment." (PMID 35763353, 2022). "In the A549 xenograft model (non-NE cancer), no complete tumor regression was observed, aligning with minimal GSPT1 degradation." (PMID 40551250, 2025). "As GSPT2 is a substitute for GSPT1, the dysregulation of GSPT2 may result in cancer drug resistance to GSPT1‐targeted therapy." (PMID 41194439, 2025). "Indeed, one of the selective GSPT1 degraders, known as MRT-2359 (Monte Rosa), was found to exhibit superior activity against MYC-dependent cancers than against cancers expressing low levels of MYC." (PMID 39875774, 2025). "GSPT1 (G1 to S phase transition 1) functions as a translation termination factor critical for cell cycle regulation and is vital for cell cycle regulation, while LPCAT1 is key for lipid remodeling and is associated with cancers and nontumor diseases." (PMID 40555906, 2025). "Integrating the results from both in vitro and in vivo experiments, we concluded that the differential anti-cancer effects of CYRS381 between NE and non-NE cancer models are primarily driven by the extent of GSPT1 degradation." (PMID 40551250, 2025). "Furthermore, according to Spearman correlation between GSPT1 and the 10 most frequently utilized E3 ligases, the expression levels of CRBN in various cancer types are not prominent; thus, we predicted the possibility of developing MGDs targeting other E3 ligases in the future." (PMID 41194439, 2025).
tumor (16 papers, 2008 to 2025). "For example, MRT‐2359 is a GSPT1‐TPD currently evaluated in phase 1 trials to target Myc‐amplified tumours, a context where all previous SMI—such as bromodomain extra‐terminal inhibitors—have failed." (PMID 40266852, 2025). "Results showed that GSPT1 was upregulated in 73.5% of tumor tissues (25/34) compared to normal tissues." (PMID 41194439, 2025). "IHC analysis of GSPT1 protein expression derived from HPA indicated that almost all 20‐examined tumor types exhibited strong or moderate GSPT1 stain." (PMID 41194439, 2025). "The significant differences of GSPT1 between normal and tumor cells are mainly in the expression level and the resulting biological effects." (PMID 41194439, 2025). "Recent studies have revealed that abnormal expression and function dysregulation of GSPT1 are significantly correlated with tumor progression." (PMID 41194439, 2025). "The core molecular and physiological function of GSPT1 is the process of protein synthesis and translation termination, which is conserved in both normal and tumor cells." (PMID 41194439, 2025). "Taken together, it can be deduced that the relationship of GSPT1 expression levels with malignancy and prognosis varies depending on the tumor type and even the tumor subtype; therefore, further studies exploring these findings are required in the future." (PMID 39117611, 2024). "Regarding the tumor-specificity of thalidomide derivatives, GSPT1 degradation triggers the integrated stress response pathway in tumor cells, resulting in apoptosis." (PMID 39117611, 2024). "Immunohistochemistry confirmed that tumor tissues from the GSPT1 knockdown group had fewer Ki67-positive cells than tissues from the control group." (PMID 33819920, 2021). "The results showed that the expression of GSPT1 is positively correlated with tumor purity, while it is negatively correlated with stromal score and immune score, which indicates that GSPT1 may have a role in tumor microenvironment remodeling." (PMID 41194439, 2025). "Therefore, to achieve precise treatment, uncovering indications for tumor cells that are highly dependent on GSPT1 is a potential strategy." (PMID 41194439, 2025). "Cleaved GSPT1 also induces cell apoptosis in tumor cells, and signaling pathways may be consistent with those in normal cells." (PMID 41194439, 2025). "In addition, tumor tissues from the GSPT1 knockdown group showed a lower degree of differentiation, abundant cytoplasm, no obvious boundary, large nuclear atypia, a high nucleocytoplasmic ratio, and an active mitotic phase relative to the control group." (PMID 33819920, 2021). "High GSPT1 expression was correlated with a larger tumor size." (PMID 33819920, 2021). "Moreover, miR-128 overexpression significantly inhibited proliferation, EMT process and tumor growth by directly targeting GSPT1 and WNT3A." (PMID 32127947, 2020). "In this study, we reported that GSPT1, which was up-regulated in CC, facilitated cell proliferation, EMT and cell cycle process, tumor growth, inhibited the apoptosis of C33A and C33A cells." (PMID 32127947, 2020). "MiR-144 has been reported to target GSPT1 to inhibit the metastasis of CRC, and miR-548c-5p has been found to act as a tumor suppressor in CRC by targeting PGK1." (PMID 31803739, 2019). "These tumor-promoting functions of ID1 appear to be brought about by STMN3 and GSPT1, which are up regulated by ID1." (PMID 25028095, 2014). "Cluster 1 was characterized by upregulation of tumor-suppressing genes: HNF1B, CCNDBP1, PATJ, EPB41L3, MARVELD2, PTEN in conjunction with cell-cycle genes – GSPT1, GPR19, EAPP, KIT, CDKL1, and stem cell markers – RBBP5, NANOG, NCSTN, ERG, including quiescent stem cell markers—FOXP1, SMARCA2." (PMID 36348001, 2022). "Chi-square tests of patients’ clinicopathological characteristics showed that high expression of GSPT1 was significantly related to larger tumor size (p=0.008), but not to stage (p=0.806), lymph node status (p=0.801), or grade (p=0.922)." (PMID 33819920, 2021).
tumor (continued). "Our results were consistent with those of the meta-analysis such that GSN, SPTBN1, SFRP1 and MAF were down-regulated in most tumor samples with respect to their matched non-tumor samples whereas COX6C, RAD21, GSPT1, NME1 and PTTG1 were up-regulated." (PMID 19116033, 2008).
infection (2 papers, 2023 to 2025). The state of being infected such as from the introduction of a foreign agent such as serum, vaccine, antigenic substance or organism. "In contrast to siRNA-mediated GSPT1 depletion, treatment with CC-90009 suppressed the accumulation of JEV RNA following infection, indicating a fundamental defect in JEV RNA synthesis." (PMID 41471039, 2025). "At the onset of the infection, UPF1 leads to a reduction in vRNA and mRNAs levels and fewer cells that are infected, while GSPT1 KD decreased the vRNA level but increased mRNA levels." (PMID 36766761, 2023). "In later infection, UPF1 and GSPT1 are hijacked, and promote viral replication." (PMID 36766761, 2023). "CC-90009 also significantly diminished the accumulation of GSPT1 and JEV non-structural proteins compared to the DMSO-treated control at 24 h post-infection." (PMID 41471039, 2025).
hematologic malignancies (1 paper, 2025). "CG009301 is a highly selective GSPT1 degrader for the treatment of R/R hematological malignancies developed by Cullgen." (PMID 41194439, 2025).
metabolic disorders (1 paper, 2025). "GSPT1 was implicated in the development of metabolic disorders through its effects on the cell cycle and protein synthesis, while LPCAT1 influenced lung function and reproductive health by regulating the phospholipid composition of cell membranes." (PMID 40555906, 2025).
GSPT1 also shares sentences with these, for which no sentence is quoted: genetic disease (2 papers); androgenetic alopecia (1); astrocytoma (1); cervical squamous cell carcinoma (1); colon adenocarcinoma (1); Esophageal Carcinoma (1); Glucose intolerance (1); hematological cancers (1); hemophilia B (1); hepatitis B virus infection (1); Insulin resistance (1); lung squamous cell carcinoma (1); mood disorder (1); Myelodysplasia (1); neuroblastoma (1); neuroendocrine carcinoma (1); non-Hodgkin lymphoma (1); Obesity (1); pancreatic adenocarcinoma (1); prostate carcinoma (1); schizophrenia (1); small cell lung carcinoma (1); triple-negative breast carcinoma (1).